CCL2 (C-C motif chemokine ligand 2)
Diseases named in the same sentence as CCL2 in open-access papers (continued):
Sharing a sentence is not in itself a finding about the gene and the disease.
prostate carcinoma (continued). "Given the immune-therapeutic potentials of CCL2 blockade against breast and prostate cancer, the CCL2-CCR2 target based approach may prove beneficial in reducing HIV/HCV co-morbidities." (PMID 25528160, 2014). "In contrast, although CCL2 signaling had only a minor effect on macrophage-induced prostate cancer cell motility, this chemokine had significant effects upon the proliferation and survival of PTEN-deficient prostate cancer cells." (PMID 24970800, 2014). "CCL2 signaling remains a promising target in advanced prostate cancer." (PMID 23698775, 2013). "Notably, tumors such as OSCC, prostate cancer and breast cancer also produce CCL2." (PMID 41445742, 2025). "Bone destruction through the activation of osteoclasts could trigger the release of tumor growth factors, while the blockade of CCL2 with specific shRNA or neutralizing antibodies could significantly impair bone resorption and prostate cancer-induced formation of osteoclasts." (PMID 37509382, 2023). "Furthermore, CCL2 released by DRGs was shown to facilitate PNI of prostate cancer cells in vitro." (PMID 37607005, 2023). "Furthermore, prostate cancer patients enrolled in a phase II clinical trial using an anti-CCL2 monoclonal antibody showed an increased CCL2 release following anti-CCL2 interruption, suggesting that a continuous arrest of CCL2 is mandatory to control tumour progression." (PMID 36161514, 2023). "It has been mentioned that activation of the CCL2/CCR2 axis could facilitate the leakage of cancer cells to other areas, enhance the secretion of MAM (metastasis-associated macrophage)-derived CCL3, and promote the bone metastasis of prostate cancer." (PMID 37509382, 2023). "Kai Sha and collaborators proved that a TNFα–CCL2 paracrine loop is induced in response to androgen deprivation therapy with enzalutamide in prostate cancer patients and might account for some forms of prostate cancer therapy resistance." (PMID 33540543, 2021). "Thus, the CCL2-CCR2axis has been suggested as a target for the treatment of prostate cancer." (PMID 34445235, 2021). "For instance, Carlumab (CNTO888), an IgG1k monoclonal antibody that binds to CCL2 showed low therapeutic effect with an increase in free CCL2 levels in phase I trials in patients with solid tumors and in a phase 2 study in metastatic castration-resistant prostate cancer." (PMID 34988021, 2021). "However, in a phase II clinical trial, was reported that carlumab (anti-CCL2 mAb) in patients with metastatic castration-resistant prostate cancer, induced a rapid rebound of the circulating concentration of free CCL2 to value higher than the pretreatment serum levels." (PMID 32849585, 2020). "Thus, CCL2 acts as a mediator of prostate cancer growth through the regulation of TAMs." (PMID 32824865, 2020). "Beyond the direct effect of KPNA4 suppression on prostate cancer cell growth, KPNA4 knockdown reduced M2 tumor-associated macrophage (TAM) infiltration into tumors in vivo by reducing chemokine (C-C motif) ligand 2 (CCL2) and chemokine (C-C motif) ligand 8 (CCL8) expression in prostate tumor cells." (PMID 29050362, 2017). "In addition, CCL2/STAT3 has been shown to stimulate prostate cancer progression." (PMID 28157698, 2017). "The increase of TAMs in prostate cancers may be mediated through prostate cancer-derived parathyroid hormone-related protein (PTHrP) which has been shown to recruit myeloid cells via osteoblast-produced chemokine (C–C motif) ligand 2 (CCL2)." (PMID 28292326, 2017). "Therefore, CCL2 may serve as a biomarker for aggressive prostate cancer with higher migration ability." (PMID 26701731, 2016). "Furthermore, prostate cancer cells with higher migration potential secrete more CCL2." (PMID 26701731, 2016). "CCL2 is one such pro-inflammatory molecule that could be targeted for anti-inflammatory strategies since CCL2 blockade strategy has already been implemented clinically in breast and prostate cancer immune-therapy." (PMID 25528160, 2014).
prostate carcinoma (continued). "Moreover, the release of CXCL8 from PTEN-depleted prostate cancer cells may act in a paracrine manner to increase the expression and secretion of CCL2 and CXCL12 from neighboring stromal cells." (PMID 24970800, 2014). "CCL2 has been previously reported as expressed in human bone marrow endothelial cells; the CCL2 stimulation promotes prostate cancer cell migration and proliferation and it has been proposed as a paracrine and autocrine factor for invasion and growth of prostate cancer." (PMID 20805891, 2010). "In prostate cancer, tumor-associated macrophages secrete pro-inflammatory cytokines such as CCL2 and CCL5, thus enhancing the migratory ability of prostate cancer cells to other parts of the body, especially the bone." (PMID 38398019, 2024). "Cytokines produced during this process, such as interleukin-6 (IL-6), tumor necrosis factor-alpha (TNF-α), and interleukin-8 (IL-8), along with chemokines like CCL2 and CCL12, are thought to be pivotal in bridging the progression to prostate cancer." (PMID 39355131, 2024). "The chemokine C-C motif ligand 2 (CCL2) and its receptor C-C motif chemokine receptor 2 (CCR2) are expressed in prostate cancer but their prognostic value is unclear." (PMID 39199567, 2024). "Our results show that CCL2 and CCR2 are expressed in prostate cancer cells, with CCL2 increased in the serum of prostate cancer patients, but the expression of both CCL2 and CCR2 exhibited no prognostic value." (PMID 39199567, 2024). "CCL2 and CCR2 protein expression in prostate cancer biopsies at the time of diagnosis were quantified by immunohistochemistry and digital quantification." (PMID 39199567, 2024). "TAMs are capable of enhancing migration of prostate cancer cells via their secretion of various cytokines such as CCL5 and CCL2 while simultaneous activation of enzymes including TRAP5b grants access to new areas of the body, e.g., bones." (PMID 36836690, 2023). "CCL2 expression has also been shown to induce secretion of CCL22, a chemokine well-studied for its role in promoting cell migration of prostate cancer." (PMID 36836690, 2023). "In prostate cancer, RON overexpression was reported to promote CCL2 production, a chemoattractant for macrophages." (PMID 36833444, 2023). "An immune-competent syngeneic murine model of prostate cancer was applied in order to assess the role of tumor cell- and MSC-derived CCL2." (PMID 36672395, 2023). "While STAT3 pathway activation led to upregulation of CCL2 and induction of EMT in prostate cancer cells, CCL5 was also found to activate STAT3 signaling." (PMID 36836690, 2023). "The interaction between CCL2 and CCR2 was reported to promote prostate-cancer cell migration via increased αvβ3 integrin production." (PMID 36289628, 2022). "In prostate cancer, WNT5A recruits and regulates macrophages through CCL2 to induce castrated prostate cancer." (PMID 35847885, 2022). "In turn, the upregulated CCL2 promotes STAT3 phosphorylation, leading to enhanced epithelial–mesenchymal transition (EMT) and metastasis of prostate cancer cells, thus promoting prostate cancer cell castration resistance." (PMID 36077785, 2022). "For instance, interleukin-1β has been shown to promote migration and proliferation of HeLa cells by targeting the NF-κB/CCL-2 pathway, while CCL2 was reported as promoting prostate cancer metastasis." (PMID 34356595, 2021). "Many studies have shown that CCL2 is closely related to tumorigenesis and is related to poor prognosis in various cancers such as HCC, lung cancer, and prostate cancer." (PMID 33891564, 2021). "Altogether, among the five cell lines we studied (two breast and three prostate cancers), four resistant clones have elevated levels of TREM1 or CCL2." (PMID 33664852, 2021). "The chemokine CCL2 is a strong chemoattractant for CCR2+ monocytes and its overexpression was reported in progressing breast cancer, prostate cancer, oral squamous cell carcinoma (OSCC), liver cancer, and colorectal cancer (CRC)." (PMID 34988021, 2021).
prostate carcinoma (continued). "C-C motif chemokine 2 (CCL2) is another cytokine, which plays a crucial role in the bone microenvironment and is produced by bone cells as well as prostate cancer cells." (PMID 34064589, 2021). "CCL2 expression is increased in AR-silenced C4-2 cells, and when AR is suppressed by ADT, prostate cancer-cell-derived CCL2, which mediates a local inflammatory response, plays a major role in tumor progression." (PMID 34445235, 2021). "TREM1/CCL2 activation, in addition to restored ASS1 expression, as a key pathway involved in full ADI-resistance in breast and prostate cancer models." (PMID 34884583, 2021). "We also found that the up-regulation of CXCL8, CCL2, CXCL10, and CCL20 expression is dependent on NF-κB activation in prostate cancer cells expressing a low level of SFMBT2." (PMID 32971847, 2020). "Similarly, type I angiotensin II receptors were reported to regulate CCL2 in prostate cancer and pancreatic cancer cells, suggesting that losartan, and potentially other type I angiotensin II receptor blockers, could be repurposed for use in cancer immunotherapy." (PMID 33297571, 2020). "We found that the down-regulation of SFMBT2 promotes the up-regulation of CXCL8, CCL2, CXCL10, and CCL20 expression in prostate cancer cells, resulting in elevated infiltration of preadipocytes and TAMs." (PMID 32971847, 2020). "Mice with LNCaP prostate cancer cell xenografts exhibited increased circulating inflammatory factors MIC1 and CCL2, and greater tumor growth when administered HFD." (PMID 33076397, 2020). "A CCL2 blockage agent (anti-human CNTO888, carlumab and anti-mouse C1142) in combination with docetaxel induce tumor regression in prostate cancer." (PMID 33062602, 2020). "We found that the down-regulation of SFMBT2 promotes the infiltration of preadipocytes and TAMs through up-regulation of CXCL8, CCL2, CXCL10, and CCL20 expression in prostate cancer." (PMID 32971847, 2020). "Expression of CXCL8, CCL2, CXCL10, and CCL20 was also elevated in prostate cancer patients having a higher Gleason score (≥8), which had substantially lower SFMBT2 expression." (PMID 32971847, 2020). "In several prostate cancer cell lines, acetyl-l-carnitine acted as an anti-prostate cancer agent by inhibiting the production of chemokines CXCL12 and CCL2 as well as CXCR4 (chemokine ligand-receptor) and pro-inflammatory cytokines (IFN-γ and TNF-α)." (PMID 32370025, 2020). "As with the expression level of CXCL8, CCL2, CXCL10, and CCL20, the number of Pref-1 or CD29 positive cells was increased in prostate cancer tissues with high Gleason scores of ≥8." (PMID 32971847, 2020). "Expression of CXCL8, CCL2, CXCL10, and CCL20 is dependent on NF-κB activation in prostate cancer cells expressing low levels of SFMBT2." (PMID 32971847, 2020). "Expression levels of CXCL8, CCL2, CXCL10, and CCL20 in prostate cancer with Gleason scores of ≥8 were higher than those with Gleason scores of ≤7." (PMID 32971847, 2020). "Further studies demonstrated that CCL2 induces CCL22 and CCR4 secretion in tumor cells stimulating migration and invasion of prostate cancer cells." (PMID 32326073, 2020). "Immunohistochemical analysis of human normal and prostate cancer tissue array consistently demonstrated the increased expression of CXCL8, CCL2, CXCL10, and CCL20 in prostate cancer tissues." (PMID 32971847, 2020). "Our analysis indicated the high expression of CXCL8, CCL2, CXCL10, and CCL20 in prostate cancer tissues expressing a low expression level of SFMBT2, which is correlated with high Gleason scores." (PMID 32971847, 2020). "Similar to pancreatic cancer, expressions of CCL2 and CCR2 were present in prostate cancer tissues and led to increased cancer proliferation and invasion through Akt signaling." (PMID 29379802, 2017). "Previously, it has been reported that co-culture of prostate cancer cells and macrophages increased CCR2 and CCL2 expression levels." (PMID 28039457, 2017).
prostate carcinoma (continued). "In vitro co-culture of prostate cancer cells and macrophages resulted in increased CCL2 and CCR2 levels in prostate cancer cells." (PMID 28039457, 2017). "The pro-inflammatory chemokines, including Chemokine (C-C motif) ligand 5 (CCL5 /RANTES), stromal cell derived factor-1 (SDF-1/ CXCL12), and monocyte chemoattractant protein-1 (MCP-1/ CCL2), are often highly expressed in prostate cancer." (PMID 29268703, 2017). "As noted in a previous study, T2A exerts cardioprotective effects through the reduction of CCL2 and TGF-β1 secretion by cardiac fibroblasts; however, the effect of DT on cytokine secretion from prostate cancer cells and macrophages is unclear." (PMID 28157698, 2017). "Therefore, CCL2 may serve as a biomarker from the time prostate cancer is diagnosed." (PMID 26701731, 2016). "We previously showed that the suppression of AR signaling not only inhibited prostate cancer cell proliferation and PSA secretion but also promoted CCL2 secretion, enabling prostate cancer cells to metastasize." (PMID 26701731, 2016). "As we expected, our study aiming to develop a novel risk classification showed that combining PSA and CCL2 predicted OS, PCaSS, and CFS of all patients with prostate cancer and those treated with ADT compared with PSA or CCL2 alone." (PMID 26701731, 2016). "The roles of monocyte chemotactic factor (MCP-1/CCL2) and NF-κB activity for co-culture induced prostate cancer invasion were tested." (PMID 26317041, 2015). "The neutralizing antibody to CCL2, named as CNTO888, decreased tumour burden and bone resorption in a mouse model of prostate cancer and combined with chemotherapy showed improved survival in pre-clinical studies." (PMID 26062132, 2015). "Interruption of this CCL2/CCR2-STAT3 axis suppressed EMT and cell migration, resulting in better suppression of tumor growth and metastasis in a xenograft prostate cancer mouse model." (PMID 25405202, 2014). "While CXCL8 was unable to induce chemokine synthesis in prostate cancer cells, CXCL8 signaling did increase CXCL12 and CCL2 synthesis in prostate stromal fibroblasts and monocytes." (PMID 24970800, 2014). "We investigated the role of CXCL8, CCL2 and CXCL12 in regulating the growth and survival of prostate cancer cells, independently or in a co-dependent manner." (PMID 24970800, 2014). "Basal mRNA expression for CCL2 and CXCL12 was lower in each of the prostate cancer cell lines relative to the expression detected in the WPMY-1 prostate stromal fibroblast or the monocytic THP-1 cell lines." (PMID 24970800, 2014). "This latter point is particularly relevant, because the prostate has frequently been shown to contain sites of inflammation, and prostate cancer expresses high levels of pro-inflammatory stimuli, including CXCR4, CCL5, and CCL2." (PMID 23362217, 2013). "One is that CCL2 negatively regulates AMP-Activated Protein Kinase to sustain mTOR Complex-1 activation, surviving expression and cell survival in human prostate cancer PC3 cells." (PMID 22248096, 2012). "In prostate cancer, apolipoprotein E (APOE) in the TME binds to TREM2 on macrophages and promotes androgen receptor (AR) expression, which further upregulates the transcription of immune mediators such as IL-10, TGF-β1, IL-23A, and CCL2." (PMID 41417432, 2025). "The identification of potential biomarkers such as APRT, CCL2, BEX2, MGC26963, and PLAU through specific gene modules and key genes could enhance our perception of prostate cancer's molecular mechanisms and targeted treatments." (PMID 38970097, 2024). "Here, we confirmed the absence of association between circulating levels of CCL2 and PSA in prostate cancer." (PMID 39199567, 2024). "However, the value of CCL2 and CCR2 as prognostic biomarkers in prostate cancer is unclear and warrant further investigation." (PMID 39199567, 2024). "Our study examined the expression of CCR2 and CCL2 protein in locally advanced prostate cancer and found that they have no prognostic value in the disease." (PMID 39199567, 2024).